TFR2 (transferrin receptor 2)
Diseases named in the same sentence as TFR2 in open-access papers (continued):
Sharing a sentence is not in itself a finding about the gene and the disease.
Anxiety (2 papers, 2016 to 2023). Intense feelings of nervousness, tension, or panic often arise in response to interpersonal stresses. "It is worth noting that these anxiety-related behaviors were iron dependent because they could be reverted by an iron deficient diet in Tfr2-KO mice." (PMID 38001850, 2023). "The marked anxious behaviour in Tfr2-KO mice suggests that Tfr2 deletion in combination with iron overload might cause an abnormal activation of the anxiety system." (PMID 27477597, 2016). "Our transcriptional and immunohistological analyses validated in Tfr2-KO mice, showed relevant Tfr2 alpha expression in the nervous tissue and revealed Tfr2 alpha protein distribution in the neurite compartment of limbic areas implicated in anxiety and stress response." (PMID 27477597, 2016). "After deletion of TfR2, which modulates systemic iron metabolism through the regulation of hepcidin, mice showed increased anxiety-like behaviors and brain iron availability." (PMID 38001850, 2023). "In order to understand the correlation of the Tfr2-KO microglial phenotype with iron overload and/or anxiety, we looked at microglia in Tfr2-KO IDD and WT IED mice." (PMID 27477597, 2016). "Based on high expression of Tfr2 in the hippocampus and limbic circuits, we examined learning abilities and anxiety in the Tfr2-KO mice by behavioural tests." (PMID 27477597, 2016). "We conclude that Tfr2 is a key regulator of brain iron homeostasis and propose a role for Tfr2 alpha in the regulation of anxiety circuits." (PMID 27477597, 2016). "Consistent with behavioural data, in Tfr2-KO mice we found a specific and selective overactivation of the limbic circuits controlling anxiety and stress responses, as demonstrated by increased expression of cFos and Zif-268." (PMID 27477597, 2016). "This pattern, together with the prominent anxious behaviour of Tfr2-KO mice, strongly suggests a role for Tfr2 alpha in the regulation of anxiety circuits." (PMID 27477597, 2016). "Notably, Tfr2-KO mice showed increased anxiety as expressed by a dramatically low frequency of entries in the open arms of the EPM." (PMID 27477597, 2016). "Thus, collectively data are consistent with a model where Tfr2-dependent alterations in iron homeostasis affect the activity of the main brain areas responsible for the neural control of emotional behaviour, and promote anxiety." (PMID 27477597, 2016). "Anxiety-like behaviours were dependent on iron increase, because they were reverted by IDD in Tfr2-KO mice." (PMID 27477597, 2016). "Moreover, microglial reactivity and degeneration occurred in both Tfr2-KO IDD and WT IED mice in the absence of an anxious phenotype, indicating that these features are also not directly linked to anxiety." (PMID 27477597, 2016). "Thus, iron alterations due to Tfr2 deficiency positively and specifically modulate neuronal activation in the CA3-CA1-mPFC-BLA circuitry, while they do not alter the neuroendocrine compartment implicated in anxiety regulation." (PMID 27477597, 2016).
Cirrhosis (2 papers, 2016 to 2019). A chronic disorder of the liver in which liver tissue becomes scarred and is partially replaced by regenerative nodules and fibrotic tissue resulting in loss of liver function. "Exosomal TfR2 can activate the p38MAPK and ERK1/2 signaling pathway in HCV-infected hepatocytes to promote carcinogenesis, and liver iron overload caused by TfR2 eventually leads to a greater range of cirrhosis and promotes HCC progression." (PMID 31815633, 2019). "HCV infection can induce the overexpression of transferrin receptor 2 (TfR2) in hepatocytes, leading to increased iron uptake and excessive deposition of iron in the liver, which eventually lead to cirrhosis." (PMID 31815633, 2019).
colon cancer (2 papers, 2013 to 2020). "TFR2 encodes a single-pass type II membrane protein involved in iron uptake and was previously found to be mutated in colon cancer and liver cancer." (PMID 23301059, 2013). "TFR2, which play a crucial role in the regulation of iron homeostasis, was found high expression in human colon cancer cell." (PMID 32375704, 2020). "In addition, 5 other mutated genes were previously reported in colon cancers including FAM181A, NRXN3, KIAA1409, TFR2, and COL4A6." (PMID 23301059, 2013). "We developed and validated a five-immune gene model of colon cancer, including LBP, TFR2, UCN, UTS2, and MC1R." (PMID 32375704, 2020).
erythroleukemia (2 papers, 2020 to 2021). Acute erythroid leukemia characterised by the presence of at least 50% erythroid precursors and at least 20% myeloblasts in the bone marrow. "It was shown that gastric cancer–derived EVs can increase pAkt and proliferation of recipient cells, and transferrin receptor 2 is released by hepatoblastoma and erythroleukemia-derived exosomes and activates signal transduction through the MAPK pathway." (PMID 34186243, 2021). "Notably, transferrin receptor 2 (TFR2) is also upregulated in different AML subtypes such as AML1, AML2, and erythroleukemia (AML6), and TFR2 α-subtype expression may be positively associated with a favorable prognosis." (PMID 33042852, 2020).
glioma (2 papers, 2022 to 2025). A benign or malignant brain and spinal cord tumor that arises from glial cells (astrocytes, oligodendrocytes, ependymal cells). "Xu Yang, Sun Qian, and Chen Qianxue’s collaborative study found that the activation of TFR2 can enhance the therapeutic efficacy of temozolomide in treating glioma." (PMID 40822852, 2025). "TFR2 is a crucial gene involved in iron transport, and its expression in gliomas is significantly higher than in other tissues." (PMID 40822852, 2025). "Iron-related gene expression in gliomas, such as TfR1 and TfR2, is different from that in other brain tumors and normal human brain tissue." (PMID 36358495, 2022). "In addition, the high expression of TfR2 not only promotes glioma cell proliferation, but also contributes to the better sensitivity to temozolomide." (PMID 36358495, 2022). "Therefore, the effect of TfR2 on glioma is still controversial, and more reports are needed to verify this." (PMID 36358495, 2022). "The proliferation of glioma cells is attributed to TfR2, which could be localized in lipid rafts and stimulate the ERK1/ERK2 phosphorylation by combining with Tf, but the mechanism of TfR2-induced glioma hypersensitivity to temozolomide remains unclear." (PMID 36358495, 2022).
heart attack (2 papers, 2020 to 2024). "Compared to HFE and TFR2‐HH, JHH carries a greater risk of heart attack, skin change, liver fibrosis, and hypogonadism, allowing easier diagnosis." (PMID 33016646, 2020).
leukemia (2 papers, 2020). A malignant (clonal) hematologic disorder, involving hematopoietic stem cells and characterized by the presence of primitive or atypical myeloid or lymphoid cells in the bone marrow and the blood. "TfR2 is mostly expressed by erythroid cell lines, normal erythroid cells at various stages of differentiation, and leukemia and pre-leukemia cells." (PMID 33334049, 2020). "TfR2 is commonly upregulated in human cancer cell lines as well, and was shown to act as a signaling protein activating the mitogen-activated protein kinase (MAPK) pathway in human leukemia cells." (PMID 33287315, 2020).
Parkinson disease (2 papers, 2021). A progressive degenerative disorder of the central nervous system characterized by loss of dopamine producing neurons in the substantia nigra and the presence of Lewy bodies in the substantia nigra and locus coeruleus. "The transferrin/transferrin receptor 2 (Tf/TfR2) transport system has been reported to deliver transferrin-bound iron to mitochondria, which is disrupted in Parkinson’s disease." (PMID 34299144, 2021).
seminoma (2 papers, 2025). A radiosensitive malignant germ cell tumor found in the testis (especially undescended), and extragonadal sites (anterior mediastinum and pineal gland). "We observed high TfR2 expression in seminomas, suggesting its involvement in tumor progression and highlighting its potential for targeted cancer therapies." (PMID 39858264, 2025). "Furthermore, the specific expression of TfR2 in seminomas highlights its potential as a therapeutic target, where its role in iron regulation and possible compensatory mechanisms warrant further investigation." (PMID 39858264, 2025). "This study investigates the immunolabeling of key iron-related proteins (Transferrin Receptor 1, Transferrin Receptor 2, and Ferritin Heavy chain 1) and Proliferating Cell Nuclear Antigen (PCNA) in canine SCO tubules within distinct microenvironments: seminomas, Sertoli cell tumors, and isolated." (PMID 40427255, 2025).
alcoholic liver diseases (1 paper, 2021). A disorder caused by damage to the liver parenchyma due to alcohol consumption. "Transferrin receptor 2 (TFR2), a carrier protein for transferrin, is involved in hepatic iron overload in alcoholic liver disease (ALD)." (PMID 34199599, 2021).
astrocytoma (1 paper, 2009). "We investigated the mRNA levels of hepcidin (HAMP), HFE, neogenin (NEO1), transferrin receptor 1 (TFRC), transferrin receptor 2 (TFR2), and hemojuvelin (HFE2) in normal human brain, brain tumors, and astrocytoma cell lines." (PMID 19386095, 2009). "The present study describes the expression of several iron-related genes including hepcidin (HAMP), HFE, neogenin(NEO1), transferrin receptor 1 (TFRC), transferrin receptor 2 (TFR2), and hemojuvelin(HFE2) in normal human brain, brain tumors, and astrocytoma cell lines." (PMID 19386095, 2009).
breast carcinoma (1 paper, 2024). "In contrast to TFR1, downregulation of TFR2 by shRNA in the high-MEMO1 breast cancer cell line results in the activation of cell proliferation." (PMID 38640016, 2024). "Conversely, knockdown or knockout of MEMO1 in breast cancer cells resulted in a statistically significant decrease in the expression levels of TFR1, TFR2, ACO1, and SLC25A28." (PMID 38640016, 2024). "Analysis of the gene expression levels in multiple breast cancer cell lines revealed weak but statistically highly significant correlations between the levels of MEMO1 and TFR1 (p=4.6E-18), TFR2 (p=1.8E-14), and PLOD1 (p=1.8E-33)." (PMID 38640016, 2024). "By comparison, breast cancer cells with MEMO1 knockout or knockdown show no proliferation rate change in response to TFR2 shRNA knockdown, indicating that TFR2 has a GOF-GI with MEMO1." (PMID 38640016, 2024). "Thus, TFR2 and SLC25A28 (mitoferrin-2) levels are markedly decreased in breast cancer cells with MEMO1 knockdown and knockout." (PMID 38640016, 2024). "Although it remains to be determined, whether a similar pathway exists in breast cancer cells that we studied, our data provide the first indication that MEMO1 and TFR2 may interact in the iron transport to mitochondria." (PMID 38640016, 2024). "Selective activation of high-MEMO breast cancer cell proliferation by TFR2 knockdown and a marked decrease in cytosolic iron concentration in the context of MEMO1 knockout suggest an important role for MEMO1 in maintaining iron homeostasis in cancer cells, likely in conjunction with TFR2." (PMID 38640016, 2024).
colon adenoma (1 paper, 2013). An adenoma that arises from the colon. "Among these mutated genes, mutations in APC, FBXW7, KIAA1409, COL4A6, FAM181A, TFR2 and NRXN3 were previously reported in colon adenomas or adenocarcinomas." (PMID 23301059, 2013).
colorectal adenocarcinoma (1 paper, 2013). The most common type of colorectal carcinoma. "The forward stepwise mode constructed discriminant functions including all genes under study, and showed that DMT1, HAMP, TfR2, miR-31, miR-149, miR-182, miR-194 were the most significant parameters responsible for progression of colorectal adenocarcinoma, assigning all cases correctly (p < 0.0001)." (PMID 24078156, 2013).
colorectal cancer (1 paper, 2023). A primary or metastatic malignant neoplasm that affects the colon or rectum. "Interestingly, expression of CA9 was positively correlated with expression of transferrin receptor 2 (TFR2) in colorectal cancer, suggesting an association between CA9 and iron transport, which is a key process associated with ferroptosis." (PMID 38099193, 2023).
Leydig cell tumor (1 paper, 2025). A sex cord-stromal tumor occurring in the testis and rarely in the ovary. "By contrast, Sertoli and Leydig cell tumors exhibited little to no TfR2 expression, emphasizing distinct patterns of iron metabolism in different tumor types." (PMID 39858264, 2025). "This study investigated TfR2 immunohistochemical expression in non-neoplastic canine testis for the first time and in the most common types of canine testicular tumors: intratubular seminomas (ITSEMs), diffuse seminomas (DSEMs), Leydig cell tumors (LCTs), and Sertoli cell tumors (SCTs)." (PMID 39858264, 2025).
lung adenocarcinoma (1 paper, 2022). A carcinoma that arises from the lung and is characterized by the presence of malignant glandular epithelial cells. "We found CD1A|CXCL13, CD1A|S100A7L2, IFNA7|CMTM2, IFNA7|CSF3, CAMP|TFR2, this 5‐IRGPs were strongly associated with the prognosis of patients, all of which were protective factors for the prognosis of lung adenocarcinoma." (PMID 35246970, 2022).
malaria (1 paper, 2024). Malaria is a serious and sometimes fatal disease caused by a parasite that commonly infects a certain type of mosquito which feeds on humans. "The higher expression of genes related to Fe uptake by erythroid cells, namely TfR1 and TfR2, in wild-type animals confirmed that mice deprived of adaptive immunity do not need much Fe to show an improved erythropoiesis during malaria." (PMID 38892340, 2024).
melanoma (1 paper, 2024). A malignant, usually aggressive tumor composed of atypical, neoplastic melanocytes. "By comparison, MEMO1 knockdown or knockout in melanoma cells decreased only the expression level of TFR2, the effect on SLC25A28 knockdown being difficult to interpret." (PMID 38640016, 2024). "MEMO1-dependent activation of cell proliferation by TFR2 knockdown, and the link between MEMO1 and TFR2 expression levels is also observed in melanoma cells, suggesting that MEMO1-TFR2 interaction has a salient role in regulating iron in various cell types." (PMID 38640016, 2024).
multiple sclerosis (1 paper, 2022). A progressive autoimmune disorder affecting the central nervous system resulting in demyelination. "In the overdominant model rs7385804 TFR2, it was shown that among patients with the AA genotype, multiple sclerosis occurs significantly more often in relatives in a straight line compared with people with the AC and CC genotypes (AA = 100.0%, AC + CC = 0.0%, p = 0.0437)." (PMID 35682458, 2022).
synucleinopathy (1 paper, 2021). A neurodegenerative disease that is characterized by the abnormal accumulation of aggregates of alpha-synuclein protein in neurons, nerve fibers or glial cells. "In summary, these results indicate that targeted TfR2 deletion had neuroprotective effects mostly in female mice in a synucleinopathy model triggered by PFF injections." (PMID 33323945, 2021).
thalassemia (1 paper, 2022). An inherited blood disorder characterized by a decreased synthesis of one of the polypeptide chains that form hemoglobin. "Potential means of improving hepcidin function in thalassemia also include acting on TMPRSS6, TfR1, TfR2 or ferroportin, the target of hepcidin." (PMID 36079046, 2022).
viral infection (1 paper, 2025). "Our findings revealed that only the sole cellular iron exporter, FPN1, but not the cellular iron importers DMT1, TFR1 or TFR2, downregulated after viral infection in mouse PMs and human THP-1 cells." (PMID 40595467, 2025). "Moreover, the membrane FPN1 levels on PMs, but not DMT1, TFR1 or TFR2, were reduced after viral infection." (PMID 40595467, 2025).
cancer (15 papers, 2013 to 2025). A tumor composed of atypical neoplastic, often pleomorphic cells that invade other tissues. "IRP2 expression profile was also significantly associated with relative expression of both genes encoding TfR in patients with stage I of cancer and additionally with TfR2 transcript level in more advanced stages of this disease." (PMID 24078156, 2013). "Less is known about its homolog, TfR2, even though its expression has been reported in various cancer types." (PMID 39858264, 2025). "In vitro investigations of iron loading or iron deprivation provided evidence that TfR2 is modulated in cancer cell lines according to cellular iron levels." (PMID 37107291, 2023). "TfR2 expression in normal tissues is restricted, but a frequent expression of TfR2 on cancer lineages of distinct origins can be observed." (PMID 36072803, 2022). "TfR2 expression in healthy adults is highly localized to the liver, but during development and in cancer, its expression is much broader, including HeLa cells as we saw in our lab (data not shown)." (PMID 30405884, 2018). "Our data support the opinion that TfR2 could specifically target SEMs neoplastic cells given its higher expression in those cancer types." (PMID 39858264, 2025). "While the use of TfR1 has already been established, less is known about TfR2 in cancer therapy." (PMID 39858264, 2025). "TfR2 is also frequently expressed in human cancer cell lines." (PMID 37107291, 2023). "EZH2 suppresses ferroptosis in HCC by downregulating TFR2, and combining EZH2 inhibitor tazemetostat with sorafenib enhances sorafenib sensitivity and anti-cancer effects." (PMID 39315094, 2024). "Finally, we discovered that the 12 IMRGs expression had significant differences, among which SFXN3, TFR2, TMPRSS6, HMOX1, and LCN2 expressions were elevated in the cancer group, and SCARA5, LTF, STEAP2, SLC39A14, CP, ALAS2, and TF were low expressed in the tumor group." (PMID 37361050, 2023).